HK1 (hexokinase 1)
Diseases named in the same sentence as HK1 in open-access papers (continued):
Sharing a sentence is not in itself a finding about the gene and the disease.
infection (25 papers, 2011 to 2025). The state of being infected such as from the introduction of a foreign agent such as serum, vaccine, antigenic substance or organism. "RelBbu-regulated sRNAs associated with genes known to be important for host infection (bosR and dhhp) as well as persistence in the tick (glpF and hk1) were identified, suggesting potential mechanisms for post-transcriptional regulation of gene expression." (PMID 30027068, 2018). "In this study, we discovered that NLRP3 deficiency in macrophages affects the expression of key glycolytic enzymes, such as Pkm and HK1, following infection." (PMID 41190868, 2025). "Among these, Hk1-Rrp1 and Rrp2-RpoN-RpoS pathways play central roles in controlling differential expression of genes critical for tick colonization and mammalian infection, respectively." (PMID 38915556, 2024). "The elevated hexokinase activity and HK1 expression levels were the most significant alterations to glycolysis in response to infection of CD4+ T cells with HIV-1 that we observed in the course of our investigations." (PMID 29518929, 2018). "Western blotting analysis revealed that the upregulation of HK1 in HIV-1 infected cells is already apparent at 24 h after infection, and this coincides with upregulation of VDAC." (PMID 29518929, 2018). "Transcripts for Hk1 and Gck showed little change during infection and Hk2 transcripts showed >1.5-fold induction." (PMID 26658723, 2015). "Hk1, which catalyzes the rate‐limiting steps of glycolysis, was expressed by the Ttr‐enriched reporter dataset Cluster 2, and this expression increased over the course of infection." (PMID 40635167, 2025). "In this study, we provide genetic evidence that the other two-component system, Hk1-Rrp1, is dispensable for mammalian infection, yet plays a vital role in the tick, in part, by controlling expression of the glycerol transport/metabolic pathway of B. burgdorferi." (PMID 21738477, 2011). "Given that the Hk1-Rrp1 pathway and the Rrp2-RpoN-RpoS pathway are the two important pathways that control differential expression of many genes essential for colonization in ticks or infection in mammals, we sought to investigate whether mcp5 is regulated by these two pathways." (PMID 38915556, 2024). "It is also apparent from our results that in addition to the expression of the PFKFB3 gene, infection of hSMs with the UT127 strain also induced higher levels of HIF1A, HK1, HK2, PDP1, and PDP2 genes compared with the infection with UT205." (PMID 35163725, 2022). "The investigation of glycolytic enzymes demonstrated activation-dependent expression of hexokinases HK1 and HK2 in human CD4+ T cells, and a highly significant increase in cellular hexokinase enzyme activity in response to infection with HIV-1." (PMID 29518929, 2018). "We therefore compared the expression levels of HK1, HK2, and VDAC in HIV-1 infected and uninfected CD4+ T cells at 24 and 48 h after infection." (PMID 29518929, 2018). "Previously, it was described in A. evenia that SYMRK, CCaMK, and the HK1 were required both in the intracellular and intercellular infection by Bradyrhizobium, reinforcing the notion of a common genetic repertoire for these types of rhizobial infection." (PMID 33793909, 2021). "Thus, unlike the concerted overexpression of all glucose transporters present in CD4+ T cells that we observed in response to infection with HIV-1, there is specificity in the upregulation of HK1." (PMID 29518929, 2018). "We therefore conclude that the HIV-1 accessory proteins are not required to mediate the upregulation of HK1, and by extension, glycolysis, upon infection of CD4+ T cells." (PMID 29518929, 2018). "The Hk1/Rrp1 two-component system, which promotes tick-adaptation during feeding but is not required for mammalian infection, is a candidate counter-regulatory pathway." (PMID 22359504, 2012).
metabolic disorders (6 papers, 2006 to 2025). "Associations with nutritional and metabolic diseases were also less important, and were mainly linked to the genes RMST, HK1, HLA-DQA1 and LAMP2." (PMID 36430729, 2022). "In our study, ovarian HK1, HK2, PDHX and ACSS2 were repressed but FBP2 and ALDH1B1 were activated in DHT-treated rats, further complicating the metabolic disorders in those groups." (PMID 25887459, 2015).
neurodegenerative disease (4 papers, 2015 to 2026). A disorder of the central nervous system characterized by gradual and progressive loss of neural tissue and neurologic function. "The increased expression of GLUT1, HK1, and PRDX2 in microglia suggests a potential mechanism for metabolic dysregulation and oxidative stress in response to inflammatory stimuli in neurodegenerative disease processes." (PMID 40888599, 2026).
neurodevelopmental disorder (3 papers, 2023 to 2025). A behavioral and cognitive disorder with onset during the developmental period that involves impaired or aberrant development of intellectual, motor, or social functions. "Notably, disorders such as neurodevelopmental disorders with visual defects and brain anomalies caused by monoallelic HK1 variants should also be differentiated." (PMID 40048124, 2025).
benign neoplasm (1 paper, 2021). A neoplasm which is characterized by the absence of morphologic features associated with malignancy (severe cytologic atypia, tumor cell necrosis, and high mitotic rate). "Meanwhile, patients with PDAC had a higher expression of RUNX1/SLC2A1/ HK1 axis than patients with benign neoplasms." (PMID 34021267, 2021).
inflammation (1 paper, 2019). Aberrant reaction of the microcirculation characterized by movement of fluid and leukocytes from the blood into extravascular tissues. "Our data suggest the possibility that variations in HK1 pathways may contribute to differences in pulmonary gas exchange that occurs during sleep, possibly through effects on ventilation-perfusion mismatch due to subclinical pulmonary inflammation." (PMID 30990817, 2019).
retinopathy (1 paper, 2013). "Moreover, for any retinopathy, there were several nominally significant associations with SNPs close to the ANK1, SLC30A8, MTNR1B, TMPRSS6 and HK1 loci." (PMID 24244560, 2013).
HK1 also shares sentences with these, for which no sentence is quoted: pancreatic ductal adenocarcinoma (6 papers); malaria (5); COVID-19 (4); leukemia (4); Allergy (3); brain tumors (3); head and neck squamous cell carcinoma (3); lymphoma (3); pancreatic adenocarcinoma (3); prostate carcinoma (3); triple-negative breast carcinoma (3); type 2 diabetes (3); autoimmune disease (2); blood disorders (2); brain cancer (2); Charcot-Marie-Tooth disease (2); clear cell renal carcinoma (2); congenital hyperinsulinism (2); cyst (2); diabetic nephropathy (2); endometriosis (2); fungal infection (2); Hashimoto encephalopathy (2); hereditary spherocytosis (2); Hyperinsulinemia (2); Insulin resistance (2); ischemia (2); medulloblastoma (2); multiple sclerosis (2); primary biliary cholangitis (2).
A further 95 diseases each share a sentence with HK1 in 2 papers or fewer.